CCNG2 (cyclin G2)
Diseases named in the same sentence as CCNG2 in open-access papers (continued):
Sharing a sentence is not in itself a finding about the gene and the disease.
ovarian carcinoma (11 papers, 2015 to 2025). A malignant neoplasm originating from the surface ovarian epithelium. "METTL3 and METTL14 form a stable heterodimer to affect the metastatic potential of cancer cells via distinct mechanism, for example, METTL3 promoted the initiation and metastasis of ovarian cancer by inhibiting CCNG2 expression." (PMID 35869392, 2022). "In ovarian cancer, cyclin G2 repressed the Wnt/β-catenin signaling pathway by downregulating key Wnt components, including DVL2." (PMID 36364346, 2022). "CCNG2 is highly unstable and can reduce cell proliferation in ovarian cancer, conceivably by inhibiting epithelial-to-mesenchymal transition, cell migration, and invasion." (PMID 34497267, 2021). "Expression determination by RT-qPCR and Western blot showed that CCNG2 expression was decreased in ovarian cancer tissues and cells, whereas the opposite effects were seen with miR-1246." (PMID 34497267, 2021). "In this study, we mainly analyzed the interaction among METTL3, miR-1246, and CCNG2 and identified their effects on progression in ovarian cancer." (PMID 34497267, 2021). "Mechanistically, METTL3 aggravated ovarian cancer by targeting miR-1246, while miR-1246 targeted and inhibited CCNG2 expression." (PMID 34497267, 2021). "Future studies will explore the possibility of regulating the METTL3/miR-1246/CCNG2 axis as targeted therapies for ovarian cancer." (PMID 34497267, 2021). "Accordingly, we used bioinformatics to detect the downstream target genes of miR-1246 in ovarian cancer, which showed that miR-1246 inhibited cyclin G2 CCNG2 expression by interacting with a binding site on the target molecule." (PMID 34497267, 2021). "Simultaneous silencing of miR-1246 and CCNG2 in IOSE80 cells reversed the promoting effect of miR-1246 on the proliferation of ovarian cancer cells." (PMID 34497267, 2021). "Taken together, these results suggest that miR-590-3p promotes ovarian cancer development, in part by directly targeting CCNG2 and FOXO3." (PMID 31013711, 2019). "We recently demonstrated that cyclin G2 exerts tumor-suppressive effects by inhibiting epithelial-to-mesenchymal transition (EMT) via suppression of Wnt/ß-catenin signaling in ovarian cancer cells." (PMID 28640887, 2017). "Since OV2008 has recently been reclassified as a cervical cancer cell line, we assessed cyclin G2 stability in several ovarian cancer cell lines." (PMID 28640887, 2017). "In addition, the maturation of pri-miR-1246 mediated by METTL3 facilitates the metastasis of ovarian cancer via repressing the cyclin G2 (CCNG2) pathway." (PMID 35804965, 2022). "Further review of related literature indicated that CCNG2 was weakly expressed in ovarian cancer." (PMID 34497267, 2021). "Accumulating evidence has suggested that CCNG2 can suppress the progression of ovarian cancer." (PMID 34497267, 2021). "However, no research has yet explored the effect of the METTL3/miR-1246/CCNG2 signaling axis in ovarian cancer." (PMID 34497267, 2021). "Therefore, we further tested the stability of cyclin G2 in several ovarian cancer cell lines and compared the results with OV2008." (PMID 28640887, 2017). "Moreover, CCNG2 promoter activity was found to be regulated by Nodal signaling in ovarian cancer cells and silencing of CCNG2 expression significantly increased cell proliferation." (PMID 25888956, 2015). "Finally, we shifted our attention to determine whether METTL3 affects the proliferation, migration, and invasion of ovarian cancer cells through the miR-1246/CCNG2 axis." (PMID 34497267, 2021). "miR‐590‐3p targets CCNG2 and FOXO3 to promote ovarian cancer development." (PMID 32892482, 2020). "Our study demonstrated that the expression and methylation level of METTL3 has a tight relationship with ovarian cancer development and further identified that METTL3 stimulated the m6A modification of miR-1246 to promote miR-1246 expression, which subsequently downregulates the expression of CCNG2." (PMID 34497267, 2021).
colorectal cancer (8 papers, 2018 to 2025). A primary or metastatic malignant neoplasm that affects the colon or rectum. "Recent research utilizing murine lung and colorectal cancer cell lines reveals that Cyclin G2, a specific protein, is integral to the expression of the macrophage IFN-γ/JAK/STAT1/CXCL9 pathway." (PMID 40909948, 2025). "In colorectal cancers, the expression of Cyclin G2 is significantly upregulated in macrophages in response to IFN-γ, leading to increased secretion of CXCL9, enhanced CTL chemotaxis, and inhibition of angiogenesis." (PMID 40909948, 2025). "Further, deletion of CCNG2 led to a decrease in cells in the G0/G1 phase in human colorectal cancer, and overexpression of CCNG2 prevented G1/S phase transformation in colorectal cancer cells." (PMID 37204480, 2023). "Finally, a recent study revealed that miR-135A1 inhibited CCNG2 to promote colorectal cancer cell proliferation." (PMID 31013711, 2019).
glioma (7 papers, 2017 to 2022). A benign or malignant brain and spinal cord tumor that arises from glial cells (astrocytes, oligodendrocytes, ependymal cells). "Through bioinformatic analysis, low expression of cyclin G2 has been implicated with high expression of Foxp3 and poor prognosis in glioma." (PMID 34452627, 2021). "Moreover, overall survival analysis revealed that high expression of cyclin G2 is associated with better overall survival in glioma patients." (PMID 34452627, 2021). "However, the potential underlying mechanisms of cyclin G2 in the glioma tumor immune microenvironment remain unclear." (PMID 34452627, 2021). "CCNG2 expression was found to be negatively associated with the pathological grade and proliferative activity of astrocytomas, as the highest expression was found in control brain tissue (N = 31), whereas the lowest expression was in high-grade glioma tissue (N = 31)." (PMID 29720957, 2018). "Our previous research found that cyclin G2 plays an anti-tumor role in a variety of cancer cells, and overexpression of cyclin G2 in glioma combined with PD-1 therapy can reverse the immunosuppressive tumor microenvironment." (PMID 36566226, 2022). "Our previous study showed that cyclin G2 inhibits tumor progression in gastric cancer, oral squamous cell carcinoma, and glioma." (PMID 36566226, 2022). "Taken together, these results demonstrate that cyclin G2 negatively correlates with tumor-infiltrating Tregs and plays an essential role in glioma progression." (PMID 34452627, 2021). "Conclusively, these findings demonstrated that cyclin G2 suppresses proliferation, migration, invasion, glycolysis and promotes apoptosis of glioma cells by inhibiting Y10 phosphorylation of LDHA." (PMID 34452627, 2021). "In the present study, we have revealed a previously uncovered role of cyclin G2 in the tumor immune microenvironment of glioma." (PMID 34452627, 2021). "Here, we described how cyclin G2 affects immune cells in TME during glioma progression as potential targets for future therapies." (PMID 34452627, 2021). "We previously demonstrated that cyclin G2 associated with LDHA and inhibited Y10 phosphorylation of LDHA in glioma cells, though the underlying mechanism remained elusive." (PMID 34452627, 2021). "Considering the anti-Warburg effect of cyclin G2, we used overexpressed cyclin G2 combined with α-PD-1 to achieve efficient metabolic therapy and immunotherapy of glioma." (PMID 34452627, 2021). "Cyclin G2 inhibited proliferation, migration, invasion capacity, and glycolysis and promoted apoptosis glioma cells via suppressing Y10 phosphorylation of LDHA." (PMID 34452627, 2021). "In conclusion, we revealed that cyclin G2 inhibits the proliferation, migration and invasion, glycolysis of glioma cells and promotes apoptosis by reducing lactate release by tumor cells." (PMID 34452627, 2021). "Expression of aberrant cyclin G2 is a key factor contributing to cancer biological processes, including glioma." (PMID 34452627, 2021). "Wilcoxon rank sum test of the relationship between CCNG2 expression in human glioma tissues and clinicopathological features." (PMID 29720957, 2018). "In this study, we attempted to decipher the molecular characterization and functional consequences of CCNG2 during the dysregulation of the glioma cell cycle." (PMID 29720957, 2018). "An increase in caspase-3 activity indicates increased apoptosis when CCNG2 is overexpressed in the glioma cell lines and Bcl-2 is downregulated." (PMID 29720957, 2018). "In this study, we found that overexpressing CCNG2 suppresses proliferation of glioma cells, arrests the glioma cell cycle, and promotes glioma apoptosis." (PMID 29720957, 2018). "Expressions of cyclin G2 and Foxp3 in glioma specimens was determined by immunohistochemistry." (PMID 34452627, 2021). "Besides, cyclin G2 potentiated PD-1 blockade and exerted strong antitumor immunity in the glioma-bearing mice model." (PMID 34452627, 2021).
glioma (continued). "Moreover, we further verified that cyclin G2 reversed the immunosuppressive to antitumor immune microenvironment through inhibiting lactate production by glioma cells." (PMID 34452627, 2021). "Moreover, overexpressed cyclin G2 levels potentiated the efficacy of PD-1 blockade in the glioma-bearing mice model." (PMID 34452627, 2021). "Glioma specimens were divided into two groups based on the expression of cyclin G2." (PMID 34452627, 2021). "Our previous study revealed that cyclin G2 inhibits aerobic glycolysis in glioma cells." (PMID 34452627, 2021). "Cyclin G2 acts as a potent tumor suppressor in glioma and enhances responses to immunotherapy." (PMID 34452627, 2021). "Relationships between CCNG2 expression in human glioma tissues and clinicopathological features." (PMID 29720957, 2018). "Propidium iodide staining and flow cytometry were used to assess whether overexpressing of CCNG2 in T98G and U251 glioma cells influenced cell apoptosis and cell cycle progression." (PMID 29720957, 2018). "In contrast, AKT activity increased in glioma cells that had low CCNG2 expression." (PMID 29720957, 2018). "Additionally, CCNG2 overexpression in glioma cell lines, T98G and U251 inhibited proliferation and arrested cells in the G0/G1 phase." (PMID 29720957, 2018). "Furthermore, inhibition of AKT kinase increased the expression of CCNG2 and also suppresses the proliferation of glioma cells." (PMID 29720957, 2018). "We found that increased CCNG2 expression could inhibit proliferation, induce G0/G1 phase arrest, and promote apoptosis in glioma cells in vitro and that levels of CCNG2 are mediated by AKT." (PMID 29720957, 2018). "We found that CCNG2 was high expression in 67% (8/12) of WHO I, 68% (13/19) of WHO II gliomas, 18% (3/17) of WHO III, and 21% (3/14) of WHO IV gliomas, indicating a loss of CCNG2 in 81% of high-grade gliomas." (PMID 29720957, 2018). "Furthermore, the expression of cyclin G2 may have prognostic significance and be utilized as a predictive biomarker to select glioma patients for immunotherapy." (PMID 34452627, 2021). "Finally, overexpression of CCNG2 in glioma cells reduced tumor volume in a murine model." (PMID 29720957, 2018). "To evaluate the ability of cyclin G2 to induce tumors to initiate PD-1 blockade and to better mimic the TME in glioma, we used GL261 cells stably expressing cyclin G2 (herein GL261-OE) and empty vector (herein GL261-EV) to inoculate C57BL/6 WT mice." (PMID 34452627, 2021). "On the contrary, Tregs primarily rely on oxidative phosphorylation, implying that cyclin G2 potentially exerts an antitumor role in glioma by reversing the acidic TME, in consideration of the inhibition of glycolysis by cyclin G2." (PMID 34452627, 2021). "Moreover, CCNG2 overexpression could increase glioma cells apoptosis." (PMID 29720957, 2018). "Results indicated a negative correlation between cyclin G2 and Foxp3, which uncovers a possible negative impact of cyclin G2 on tumor-infiltrating Tregs in glioma." (PMID 34452627, 2021). "Thus, we established a syngeneic mouse tumor model by subcutaneously inoculating mouse glioma cell line GL261 in C57BL/6 WT and Ccng2−/− mice." (PMID 34452627, 2021). "Moreover, in this study, we confirmed the negative correlation between cyclin G2 and Foxp3 in glioma specimens." (PMID 34452627, 2021). "However, the role of cyclin G2 in modulating the immune microenvironment of glioma had not been explored." (PMID 34452627, 2021).
prostate carcinoma (7 papers, 2012 to 2025). A carcinoma that arises from epithelial cells of the prostate gland. "Further, the Kaplan–Meier survival plot for CCNG2 in prostate cancer suggests that low CCNG2 expression is linked with diminished survival rates in PCa over time suggesting that CCNG2 is part of a tumor suppressive program induced by SAL." (PMID 38902772, 2024). "It was reported to have tumor suppressor functions in different neoplasias, although, supporting our observations, CCNG2 positively associated with prostate cancer recurrence after radical prostatectomy." (PMID 28938627, 2017). "In contrast, androgen-repressed genes that inhibit prostate cancer proliferation, such as CCNG2 and CDKN1A, were induced by LLS30." (PMID 39941722, 2025). "CCNG2 is exclusively expressed in quiescent cancer cells; CCNG2 transfection reduces survival of prostate cancer cells." (PMID 28729699, 2017). "These represented cell cycle/mitosis; among others CCNE1, CCNE2, CCNG2, CCNL1, CCNT1, CDK12 and CDKN3, prostate cancer; including the androgen receptor (AR), metabolism as well as targets of the transcription factors E2F, AP2, SP1, ETF and Pax3." (PMID 26698305, 2015).
colon cancer (6 papers, 2016 to 2024). "To determine if loss of cyclin G2 had a similar effect on other cancers, we used colon cancer cells for further experiments." (PMID 36566226, 2022). "Upregulated cyclin G2 inhibited lung and colon cancer growth by increasing the secretion of its downstream effector CXCL9, which promoted CTL chemotaxis and suppressed vascular endothelial cell tube formation." (PMID 36566226, 2022). "Although we only explored the role of cyclin G2 in lung and colon cancers, macrophages are ubiquitous in the tumor microenvironment of various cancers and have crucial functions." (PMID 36566226, 2022). "Since FXR is downregulated in CRC, the activation of FXR by GW4064 induces CCNG2 expression in a miR-135A1-dependent manner in vitro to hinder cell cycle progression and growth of colon cancer cells." (PMID 36278234, 2022). "The expression level of CycG1 (CCNG1) was reduced in bladder cancer, head and neck cancer, and sarcoma relative to normal solid tissue, whereas CycG2 (CCNG2) expression was reduced in colon cancer, head and neck cancer, and rectal cancer." (PMID 27982046, 2016). "eQTL analyses for this SNP showed differential expression of CCNG2 in colon tumor tissues." (PMID 38664626, 2024). "We found that subcutaneous lung and colon tumors grew larger after cyclin G2 deletion from macrophages after IFN-γ treatment, indicating that cyclin G2 in macrophages alters the tumor microenvironment and plays a key role in tumor suppression mediated by IFN-γ-stimulated macrophages." (PMID 36566226, 2022). "MiR-135A1 is highly produced in colon cancer specimens along with cell lines, while the level of the clinical significance of cyclin G2 (CCNG2), which can inhibit cell proliferation and promote apoptosis, is negatively correlated with miR-135A1 in human CRC tissues." (PMID 36278234, 2022). "Our results suggested that the function of cyclin G2 may be the same in many tumor types, including lung and colon cancer." (PMID 36566226, 2022). "In addition, it was found that FXR activation by GW4064 in colon cancer cell lines, SW620 and HCT-116 upregulated the expression of cyclin G2 (CCNG2) by suppressing miR-135A1, which leads to reduced cell proliferation and induction of cell cycle arrest." (PMID 38372868, 2024).
lung carcinoma (4 papers, 2017 to 2022). "We previously found that cyclin G2 knockout in macrophages attenuated the antitumor effect of IFN-γ on lung cancer." (PMID 36566226, 2022). "miR-135b has also been reported to target CCNG2 and exert tumor-promoting effects in lung cancer." (PMID 31013711, 2019).
neuroblastoma (4 papers, 2015 to 2022). Neuroblastoma (NB) is the most common solid, extracranial childhood tumor. "When MYCN was knocked-down by RNAi in selected neuroblastoma cell lines, cyclin A1 (CCNA1, OMIM 604036) and cyclin G2 (CCNG2, OMIM 603203) were upregulated alongside the cyclin-dependent kinase inhibitor CDKN1C, suggesting a functional connection between MYCN amplification and cell cycle control." (PMID 35804856, 2022).
glomerulosclerosis (3 papers, 2018 to 2020). A hardening of the kidney glomerulus caused by scarring of the blood vessels. "In the article titled “Cyclin G2 Suppresses Glomerulosclerosis by Regulating Canonical Wnt Signalling”, there was an error in the Acknowledgments section where the grant numbers “(nos." (PMID 31058189, 2019). "Our findings delineate a previously unidentified function of cyclin G2 as a protector in the pathologic progression of glomerulosclerosis in DN." (PMID 30420966, 2018). "We found that cyclin G2 contributes to suppressing the occurrence and development of glomerulosclerosis in DN by regulating canonical Wnt signalling." (PMID 30420966, 2018). "Conversely, cyclin G2 knockout increased expression of glomerulosclerosis-related proteins in the mouse kidney." (PMID 30420966, 2018). "To evaluate whether cyclin G2 inhibited the expression of glomerulosclerosis-related proteins under high-glucose conditions, we cultured HMC cells in a high concentration of glucose for 72 h, which led to the upregulation of FN and collagen IV." (PMID 30420966, 2018). "In the present study, we conducted cyclin G2 knockout studies to determine whether this protein regulates glomerulosclerosis in DN mice." (PMID 30420966, 2018). "In the absence of CHIR99021, cyclin G2 overexpression inhibited the expression of proteins associated with canonical Wnt signalling and glomerulosclerosis." (PMID 30420966, 2018). "Furthermore, treatment of HMC cells with the GSK3β inhibitor CHIR99021 (activator of Wnt signalling) abrogated the inhibitory effects of cyclin G2 on canonical Wnt signalling and glomerulosclerosis-related proteins." (PMID 30420966, 2018). "Therefore, cyclin G2 is protective against DN progression, specifically against glomerulosclerosis." (PMID 30420966, 2018). "To evaluate the effect of cyclin G2 on glomerulosclerosis, we overexpressed cyclin G2 in HMC cells using lentiviral (LV-CCNG2) transduction and analysed the expression of glomerulosclerosis-related proteins." (PMID 30420966, 2018). "By overexpressing cyclin G2 in HMC cells, we found that cyclin G2 significantly inhibited the expression of glomerulosclerosis-related proteins." (PMID 30420966, 2018). "Involvement of cyclin G2 in the process of glomerulosclerosis in diabetes has not been reported previously." (PMID 30420966, 2018).
laryngeal squamous cell carcinoma (3 papers, 2019 to 2024). A squamous cell carcinoma that arises from the larynx. "Furthermore, miR-93 targeted CCNG2 to exert tumor-promoting effects in laryngeal squamous cell carcinoma." (PMID 31013711, 2019).
oral squamous cell carcinoma (3 papers, 2019 to 2024). "This study aimed to investigate the effect of cyclin G2 on oral squamous cell carcinoma (OSCC)." (PMID 33240810, 2020). "Also, the cancer stemness of oral squamous cell carcinoma cells is enhanced by miR-1246, which targets cyclin G2 (CCNG2)." (PMID 31861937, 2019).